SHPRH (SNF2 histone linker PHD RING helicase)
Diseases named in the same sentence as SHPRH in open-access papers (continued):
Sharing a sentence is not in itself a finding about the gene and the disease.
lung carcinoma (1 paper, 2024). "One of the genes, SHPRH, was of particular interest due to its frequency of double allelic alterations and location in a lung cancer susceptibility region." (PMID 38890444, 2024). "SNF2 Histone Linker PHD RING Helicase (SHPRH) was uncovered as a candidate of interest due to its frequency of double allelic disruption and location within the main lung cancer susceptibility locus on chromosome arm 6q." (PMID 38890444, 2024). "In doing so, SHPRH may become an important genetic marker to identify at-risk individuals for lung cancer and to highlight a targetable vulnerability in these patients." (PMID 38890444, 2024). "Because of the predicted functional impact in our tumor population, the frequency of double allelic disruptions in the expanded datasets, and its chromosomal location in a major lung cancer susceptibility region, we propose that SHPRH is a candidate tumor suppressor gene in LUAD." (PMID 38890444, 2024). "Because of its role in DNA damage tolerance, SHPRH may work to counteract the effects of lung cancer risk factors, such as smoking, environmental factors, and intrinsic cellular DNA damage, in order to help prevent lung cancer development and progression." (PMID 38890444, 2024). "Because SHPRH resides within this lung cancer susceptibility region at chromosome 6q24.3 and is an appealing candidate for a tumor suppressor gene with an implicated association with LUAD, further investigation into its role in lung cancer risk and development would be of interest." (PMID 38890444, 2024). "Lastly, expression of SHPRH was significantly reduced in LUAD (N = 58) in comparison to normal lung epithelium from individuals without lung cancer (N = 67), suggesting that SHPRH is downregulated/inactivated during cancer development, consistent with a tumor suppressive function." (PMID 38890444, 2024).
nasopharyngeal carcinoma (1 paper, 2014). A carcinoma arising from the nasopharyngeal epithelium. "UBC13, HLTF, and SHPRH in the TS pathway, RAD51 and BRCA1 in the HR pathway, and FANCD2 in the FA pathway are highly expressed in cisplatin-resistant nasopharyngeal carcinoma (NPC) cells." (PMID 25051366, 2014).
retinoblastoma (1 paper, 2023). A malignant tumor that originates in the nuclear layer of the retina. "Furthermore, Fisher’s exact test showed that circ-SHPRH was significantly related to cancer volume (p = 0.017) and advanced intraocular international retinoblastoma classify (IIRC) stage (p = 0.01)." (PMID 37305675, 2023).
uterine cancer (1 paper, 2018). Primary or metastatic malignant neoplasm involving the uterine corpus and/or the cervix. "Methylation of MLH1 and SHPRH are both associated with mutational signature 6, with a stronger association in uterine cancer." (PMID 30217226, 2018). "Despite these constraints, we successfully identified a novel association between methylation of SHPRH and somatic MSI burden, with a particularly strong effect in uterine cancer where SHPRH methylated individuals exhibit a 2.4 fold increase in somatic MSI burden." (PMID 30217226, 2018). "We observed that methylation of SHPRH has the strongest effect both on SHPRH expression and somatic MSI burden in uterine cancer." (PMID 30217226, 2018).
tumor (36 papers, 2014 to 2025). "Because of its location within this susceptibility locus, SHPRH was determined to be the focus of our subsequent follow up to evaluate its candidacy as a tumor suppressor gene in LUAD." (PMID 38890444, 2024). "Patients with reduced plasma circ-SHPRH levels had a higher risk of early tumor recurrence and poor prognosis." (PMID 37305675, 2023). "For example, “circ-SHPRH” can encode the SHPRH-146 amino acid protein, which acts as a tumor suppressor." (PMID 36230649, 2022). "While other potential tumor suppressors have also been identified within this region, several studies have further linked SHPRH to cancer." (PMID 31434570, 2019). "Furthermore, SHPRH was found to be truncated or to contain missense mutations in tumor cell lines, which is consistent with a tumor-suppressor function." (PMID 29807746, 2018). "circ-SHPRH upregulated the crucial cell cycle regulator p21 expression to block cyclin-dependent kinases in NB, and circ-SHPRH overexpression limited NB tumor growth in NOD scid gamma mice." (PMID 40331938, 2025). "Lastly, we aimed to confirm that inactivation of SHPRH can have a tumor promoting effect by knocking out SHPRH with CRISPR in a LUAD cell line with wildtype status (A549) and performing the same in vivo experiments." (PMID 38890444, 2024). "SHPRH-146aa functions as a GBM tumor suppressor by protecting SHPRH, a known tumor suppressor, from ubiquitination." (PMID 39333489, 2024). "Together, this data phenotypically characterizes SHPRH as a tumor suppressor that acts to reduce tumorigenesis in LUAD cells with inactivating alterations of SHPRH." (PMID 38890444, 2024). "This demonstrated that cells with SHPRH knockout had increased growth and tumor size at endpoint compared to their SHPRH expressing counterparts, further supporting the role of SHPRH in tumor suppression." (PMID 38890444, 2024). "It was found that SHPRH-146aa is a tumor suppressor protein that prevents SHPRH full-length protein from degradation, suggesting that aberrant translation of circSHPRH affects tumor malignancy." (PMID 37296107, 2023). "Further exploration of the tumor suppressor mechanism showed that circ-SHPRH inhibited RB proliferation and promoted RB apoptosis by regulating the AKT/mTOR signaling pathway." (PMID 37305675, 2023). "Fisher’s exact test results show that the level of circ-SHPRH is closely related to the volume and degree of differentiation of the tumor." (PMID 37305675, 2023). "In this review, we introduce many novel features of circ-SHPRH to further understand the role of circ-SHPRH in regulating gene expression in tumorigenesis and tumor progression." (PMID 37305675, 2023). "Functionally, circ-SHPRH has been shown to be a tumor suppressor that inhibits tumor progression in a variety of cancers." (PMID 37305675, 2023). "Numerous studies have revealed correlations between circ-SHPRH and tumor clinicopathological features." (PMID 37305675, 2023). "This novel protein protects the full-length SHPRH from DTL-induced ubiquitination, leading to an increase in full-length SHPRH’s half-life and induces the protein’s tumor suppressive functions." (PMID 35090496, 2022). "SHPRH-146aa is a tumor suppressor that can protect the full-length SHPRH protein from being degraded by the ubiquitin proteasome, thereby promoting the turnover of proliferating cell nuclear antigen in vivo." (PMID 34526007, 2021). "Consistently, immunostaining of xenografted tumor tissues showed upregulated expression of Ki-67 and downregulated expression of SHPRH and E-cadherin in the sh-circ-0001649 group." (PMID 31137016, 2019). "The circ-SHPRH protected the host protein from degradation, thus increasing the tumor suppressive activity of the gene." (PMID 31861825, 2019). "In this study, SHPRH was positively associated with circ-0001649 and lowly expressed in HCC cell lines and tumor tissues." (PMID 31137016, 2019).
tumor (continued). "The multiple activities and overlapping domains seen for Rad5 are conserved among its homologs, including the human tumor suppressors SHPRH and HLTF (reviewed in 2,23)." (PMID 25690888, 2015). "As a key tumor suppressor, SHPRH contributes to the inhibition of tumorigenesis and progression." (PMID 38544689, 2024). "Across several cancer types, there has been an observed loss of heterozygosity of chromosome 6q24, further suggesting that SHPRH – located at 6q24.3 – may have a tumor suppressive role in cancer." (PMID 38890444, 2024). "Consequently, these findings underscore the potential role of circ-SHPRH in facilitating apoptosis, thereby exhibiting a tumor-suppressive effect in NB." (PMID 38282862, 2024). "Indeed, TetO SHPRH cells show a significant reduction in tumor growth and size in mice kept on a dox diet, whereas TetO SHPRH cells implanted into mice kept on a normal diet do not show a significant difference in comparison to the GFP control." (PMID 38890444, 2024). "To confirm the clinical relevance of these findings, we next performed GSEA on LUAD patient tumor mRNA expression data (N = 510) in order to identify the top gene sets that are negatively correlated with SHPRH expression, in concordance with SHPRH’s proposed function as a tumor suppressor gene." (PMID 38890444, 2024). "To investigate the mechanism by which SHPRH may operate as tumor suppressor in LUAD, we next set out to perform RNAseq on the NCI-H1395SHPRH-DEL cells which do not basally express SHPRH." (PMID 38890444, 2024). "As such, despite the overwhelming evidence suggesting that full-length SHPRH may be a tumor suppressor in multiple cancer types, the functional characterization of it as a tumor suppressor gene has yet to be exhibited." (PMID 38890444, 2024). "They found that downregulated circ-SHPRH was related to larger tumor size and advanced grade." (PMID 37305675, 2023). "Furthermore, the lower the circ-SHPRH expression in the tumor, the larger the tumor volume, which suggests that circ-SHPRH is related to tumor growth." (PMID 37305675, 2023). "According to current research, SHPRH plays a tumor suppressing function in cancer." (PMID 37305675, 2023). "Three eligible published studies about circ-SHPRH were enrolled based on their tumor diagnosis aspect, 7 eligible published studies were related to overall survival (OS), and 3 eligible published studies were related to tumor grade." (PMID 37305675, 2023). "A role for SHPRH in preventing genomic instability is consistent with tumor suppressor functions." (PMID 31434570, 2019). "Together, this suggest that SHPRH may be inactivated in many aggressive solid cancer types in addition to LUAD, with recurrent mutations providing potential evidence of positive selection during tumor evolution." (PMID 38890444, 2024). "In addition, circ-SHPRH may also become a new tumor marker candidate, providing a new target for the diagnosis and prognosis of different types of cancer." (PMID 37305675, 2023). "Although several studies have revealed the correlation of tumor clinicopathological features with circ-SHPRH, retrospective and prospective studies of large patient samples are still needed to provide more evidence to support the correlation of circ-SHPRH with specific cancers." (PMID 37305675, 2023). "Circ-SHPRH expresses an isoform of histone-linker PHD and RING finger domain-containing helicase (SHPRH), the 17 kDa protein SHPRH-144aa, which has a role in tumor suppression." (PMID 33202605, 2020). "Two Rad5-related DNA translocases in human cells, HLTF and SHPRH, are tumor suppressors which prevent genomic instability." (PMID 30764567, 2019). "Furthermore, we demonstrate that re-expression of SHPRH in LUAD cells with inactivating alterations reduces their tumorigenic potential in vitro and in vivo, highlighting SHPRH as a novel tumor suppressor gene in LUAD." (PMID 38890444, 2024).
tumor (continued). "The frequency of double allelic alterations in SHPRH and ASCC3 suggest that they may be candidate tumor suppressor genes in LUAD, whereby their inactivation could contribute to LUAD development and progression." (PMID 38890444, 2024). "Furthermore, we showed that re-expression of SHPRH in LUAD cell lines with inactivating alterations for SHPRH reduces their in vitro colony formation and tumor burden in vivo." (PMID 38890444, 2024). "The SHPRH (SNF2, histone linker, PHD, RING, helicase) subfamily belonging to ATP-dependent chromatin remodeling factor is the effective tumor-suppressor, which can polyubiquitinate PCNA (proliferating cell nuclear antigen) and participate in post-replication repair in human." (PMID 36987072, 2023). "In effort to identify early events which may be driving the tumor suppressive phenotype that is observed in these cells upon re-expression of SHPRH, RNA was collected from TetO GFP and TetO SHPRH cells treated with or without dox for 72 h and then profiled." (PMID 38890444, 2024). "Furthermore, the results of circ-0001649 and SHPRH levels in HCC tumors and paired adjacent nonmalignant tissues showed significantly lower circ-0001649 and SHPRH in HCC tumor tissues." (PMID 31137016, 2019).
cancer (24 papers, 2007 to 2025). A tumor composed of atypical neoplastic, often pleomorphic cells that invade other tissues. "Circ-SHPRH originates from exons 26–29 of the SHPRH gene, and it is closely associated with human cancers." (PMID 37305675, 2023). "The SHPRH-146aa protein translated from the circular RNA circ-SHPRH was also characterized recently as the first circRNA-encoded protein associated with cancer pathogenesis." (PMID 35071227, 2021). "Has_circ_0001649, transcribed from an antioncogene SHPRH, is a novel cancer-associated circRNA found in several cancers, such as cholangiocarcinoma." (PMID 33015046, 2020). "Mutations in the SHPRH gene occur in various cancer cell lines, including those of ovarian cancer and melanoma." (PMID 32781555, 2020). "More specifically, silencing of SHPRH is associated with one of the characteristic cancer mutational signatures (mutational signature 6), which is common in uterine cancer." (PMID 31434570, 2019). "ncRNA encoded peptides/proteins (HOXB-AS3, FBXW7-185aa, SHPRH-146aa, miPEP-200a, and miPEP-200b) have been proved to suppress tumorigenesis, which has enriched the research of ncRNAs in cancer development." (PMID 30483132, 2018). "Methylation of SHPRH was associated with a 16% decrease in gene expression in a pan-cancer analysis." (PMID 30217226, 2018). "Moreover, circ-SHPRH encodes SHPRH-146aa, a key regulator of cancer cell proliferation and tumorigenicity in vitro." (PMID 38035041, 2024). "Many studies have shown that circ-SHPRH acts as a miRNA sponge or encodes a protein to regulate downstream genes or signal pathways, and exerts specific biological functions that affect the proliferation, invasion, and apoptosis of cancer cells." (PMID 37305675, 2023). "Hsa_circ_0001649, a transcriptional product of the tumor suppressor gene SNF2 histone linker PHDRINGhelicase (SHPRH), is a novel cancer-associated circRNA that exhibits decreased expression in several cancer types, including cholangiocarcinoma, hepatocellular carcinoma and colorectal cancer." (PMID 32698139, 2020). "Furthermore, HLTF and SHPRH are frequently inactivated in various cancers, and their loss increases the frequency of chromosome abnormalities during DNA damage indicating their importance in the maintenance of genomic stability and cancer suppression." (PMID 26350214, 2015). "The protein coding genes ZNRD1, RNF39 and PPP1R11, along with the ncRNA ZNRD1-AS1, have been associated with disease states that are related to autoimmunity, immunity, and infection; while EPM2A and SHPRH have been associated with glycogen metabolism, cancer, and chemical dependency." (PMID 25642351, 2014). "Furthermore, assessment across cancer types revealed recurrent mutation sites in SHPRH, including mutations at G458 (non-sense or frameshift deletions in 8 cases, including LUAD), G587 (missense or frameshift deletions/insertions in 8 cases) and R1365 (R1365C in 5 cases)." (PMID 38890444, 2024). "Besides the better studied translated circZNF609, which harbors IRES elements and undergoes cap-independent translation, cancer-associated examples of translated circRNAs include the circular form of the SHPRH gene (circSHPRH) which encodes the novel identified protein termed SHPRH-146aa." (PMID 37587333, 2023). "In human cells, Rad5 orthologs HLTF and SHPRH catalyze similar PCNA ubiquitination reactions and are implicated in many diseases including several types of cancer." (PMID 39826694, 2025). "This review will help enrich our understanding of the role and mechanism of circ-SHPRH in human cancers." (PMID 37305675, 2023). "The down-regulation of circ-SHPRH expression results in the increased proliferation, migration, and invasion of cancer cells." (PMID 32781555, 2020). "With the emergence of in vitro synthesis of circRNA technology, synthetic drugs targeting circ-SHPRH may become a treatment choice for certain cancers in the future." (PMID 37305675, 2023).
cancer (continued). "ACTL6A, CHD2, and ACTB had the highest pan‐cancer G‐score for amplification, whereas CHD5, SHPRH, INO80, and ACTR8 had the highest pan‐cancer G‐score for deletions." (PMID 35789070, 2022). "Both HLTF and SHPRH were found to be down-regulated in several cancer types and HLTF is also up-regulated in various cancer types." (PMID 34407997, 2021). "Additionally, SHPRH‐146aa protects SHPRH from the degradation of the ubiquitin proteasome and promotes the ubiquitination of proliferating cell nuclear antigen (PCNA), reducing the malignant behavior of cancer cells in vivo and in vitro." (PMID 34097315, 2021). "In addition, cancer patients who show resistance to HU treatment might have elevated levels of HLTF and SHPRH which tolerate the damage induced by the cancer drug." (PMID 34407997, 2021).
neurodegenerative disease (1 paper, 2025). A disorder of the central nervous system characterized by gradual and progressive loss of neural tissue and neurologic function. "circ-SHPRH is a natural circRNA that encodes a protein called SHPRH-146aa, which is involved in the onset of neurodegenerative diseases." (PMID 40034125, 2025).
SHPRH also shares sentences with these, for which no sentence is quoted: infection (3 papers); bladder cancer (2); breast carcinoma (2); gastric cancer (2); melanoma (2); Aicardi Goutières syndrome (1); cervical carcinoma (1); cholangiocarcinoma (1); cutaneous melanoma (1); endometrial carcinoma (1); epilepsy (1); esophageal squamous cell carcinoma (1); Huntington disease (1); lung adenocarcinoma (1); myotonic dystrophy (1); non-small cell lung carcinoma (1); Recurrent infections (1); stomach adenocarcinoma (1); systemic lupus erythematosus (1).